IL6 (interleukin 6)
Diseases named in the same sentence as IL6 in open-access papers (continued):
Sharing a sentence is not in itself a finding about the gene and the disease.
myeloma (continued). "However, the role of c-Met as a regulator of IL-6-induced Ras-MAPK signaling has to our knowledge not been shown in myeloma cells before." (PMID 19187270, 2009). "Also in the myeloma cell lines OH-2 and IH-1 similar results were seen: HGF alone did not increase proliferation but potentiated the effect of IL-6, and likewise, incubation with IL-6 increased the expression of c-Met." (PMID 19187270, 2009). "To exclude the presence of myeloma "long-living" contaminants, or possible myeloma precursors in the transduced and selected cell fraction, we seeded CD34+/ΔLNGFR+ cells of patient MM18 in a LTMC assay, adding IL6 to the culture to favour the maintenance of the plasma cells in culture." (PMID 17626627, 2007). "Our results demonstrated an increase in the IL-6 secretion by BeWo cells in response to T. gondii infection, as previously reported, and the HO-1 induction by hemin treatment also enhanced the release of this cytokine, regardless of infection, as observed in myeloma cells." (PMID 33912151, 2021). "Hence, in myeloma cells, NonO could be recruited to a PRDM1 complex but no PRDM1-mediated regulatory effects on IL-6 expression by NonO-deficiency and PRDM1-deficiency were observed." (PMID 32765503, 2020). "However, a limitation of this method is that IL-6 is not just produced by myeloma cells so this may not be the most accurate way to monitor BHQ880 activity." (PMID 29098361, 2018). "Notably, addition of insulin-like growth factor 1 and interleukin-6, two important triggers for PI3K activation in MM cells, partly blocked BENC-511-induced MM cell death, which further demonstrated that PI3K signaling pathway was critical for the anti-myeloma activity of BENC-511." (PMID 24428908, 2014). "In 2017, it was again reported to be a promising agent for inhibiting myeloma cell growth, interestingly reducing the phosphorylation of STAT3 but not ERK in response to IL-6 and LIF stimulation." (PMID 40895548, 2025). "Treatment for 24 hours with myeloma conditioned media obtained from OPM2 but not U266 HMCLs induced ARG1 in healthy HDNs, while nor IL6 neither LPS did not induce any change in the amount of intracellular ARG1." (PMID 32029833, 2020). "In the absence of IL6, two other cytokines, B-cell activating factor (BAFF) and a proliferation inducing ligand (APRIL) have been shown to have a protective effect on myeloma cells particularly from treatment with corticosteroid." (PMID 33634031, 2020). "IL6 and IL6R also play important roles in the development of several hematological malignancies, including myeloma, B-cell leukemias, lymphomas and non-B cell malignancies." (PMID 32957689, 2020). "Phosphorylation and nuclear localization of STAT1 in response to IL-6 is comparable in CD45+ and CD45- myeloma cells, indicating that CD45 does not regulate STAT1 phosphorylation." (PMID 25781885, 2015). "In contrast, although IL-6 and APRIL supported myeloma growth in some high density cultures, this effect was not consistent." (PMID 25272036, 2014). "Addition of IL-6 and APRIL together did not result in increased myeloma growth compared to supplement with one cytokine alone." (PMID 25272036, 2014). "However, in patients with relapsed-refractory multiple myeloma (RRMM), there was no benefit to the addition of siltuximab, an IL-6 inhibitor, to bortezomib and/or dexamethasone-containing treatment regimes in non-transplant settings." (PMID 33777050, 2021). "Since plasma cells express a high level of PRDM1 and secrete IL-6, we wanted to know whether PRDM1 and NonO regulate IL-6 in the human myeloma B cell lines, U-266, and RPMI-8226 since both cell lines express a high level of PRDM1 and NonO." (PMID 32765503, 2020). "In order to test whether these cytokines also promote the growth of MOPC315.BM cells, either 103 (low density) or 104 (high density) of these murine myeloma cells were cultured in 96-well plates, in medium containing either 1% or 5% FCS and with or without supplement of IL-6 and/or APRIL." (PMID 25272036, 2014).
prostate carcinoma (639 papers, 2002 to 2026). A carcinoma that arises from epithelial cells of the prostate gland. "In prostate tissue, inflammation has been linked to the production of interleukin-6 (IL-6) and interleukin-2 (IL-2), cytokines strongly implicated in prostate-cancer pathogenesis." (PMID 41375042, 2025). "CNP and prostate carcinoma patients are associated with prolonged overproduction of inflammatory cytokines, including IL‐1β, IL‐6, and TNF‐α." (PMID 40552335, 2025). "In patients with CRPC undergoing Doc chemotherapy, increased baseline serum IL-6 levels are inversely associated with treatment response, time to progression, and both prostate cancer-specific and overall survival." (PMID 40507238, 2025). "IL-6 plays a pivotal role in prostate inflammation and has been implicated in the progression of prostate cancer." (PMID 39125867, 2024). "IL-6 and other inflammatory cytokines are implicated in treatment resistance of prostate cancer and are affected by ADT." (PMID 38256338, 2023). "We observed that genetic predisposition to IL-6 levels were positively related with prostate cancer risk, and the result was consistent with previous observational studies." (PMID 36733309, 2023). "CHD1 has been shown to active NF-κB in PTEN-deficient prostate cancer cells, which in turn promotes the secretion of IL-6." (PMID 37190171, 2023). "Higher levels of IL-6 were associated with higher phenotypic frailty in prostate cancer during androgen deprivation treatment (ADT) and at one-year follow-up." (PMID 37213604, 2023). "The association of inflammatory cytokines such as IL-6 and cognitive impairment in both prostate cancer patients undergoing ADT and AD patients merits further scrutiny with a focus on both cognitive measures and physiological effects." (PMID 38256338, 2023). "For example, prostate carcinoma-secreted IL-6 can increase the expression of the cancer-associated fibroblast marker FAP, activating human prostate fibroblasts and enhancing the invasive ability of prostate cancer." (PMID 37821959, 2023). "After excluding these potential pleiotropic SNPs, the associations between IL-6, IL-27 and prostate cancer risk remained consistent in the sensitivity analyses." (PMID 36733309, 2023). "Our MR study found that genetic liability to IL-1ra and IL-6 levels were associated with the risk of prostate cancer." (PMID 36733309, 2023). "In this study, high serum IL-6 levels were associated with the advanced stages of prostate cancer and poor survival rate." (PMID 36140220, 2022). "Among these include Il6 which has been previously implicated in the promotion of prostate cancer both in vitro and in vivo." (PMID 35911788, 2022). "The increased serum levels of IL-6 during the course of radiotherapy in patients with prostate cancer had been reported to be significantly associated with higher grade of acute GU toxicity across radiotherapy." (PMID 36368974, 2022). "The IL-6 rs1800795 (-174G/C) polymorphism is a significant predictor for susceptibility of prostate cancer and bone metastasis in northwest Iranian population." (PMID 33684135, 2021). "IRE1α formed a positive feedback loop with IL-6 and AR to promote prostate cancer cell proliferation under the androgen-deficient condition." (PMID 34295814, 2021). "Increased levels of interleukin-6 (IL-6) have been linked to poor survival among prostate cancer patients, and it is known that CAFs secrete high levels of IL-6 into the TME." (PMID 33535458, 2021). "IL-6 activation of the androgen receptor in some prostate cancers is associated with increased growth in vitro and in vivo." (PMID 34204596, 2021). "In another study, carcinogenesis and enhanced tumour aggressiveness in prostate cancer due to an elevated level of interleukin-6 (IL-6) is linked to the down-regulation of the Anx-A1 level." (PMID 32823805, 2020). "Based on epidemiological studies, higher IL-6 levels are associated with prostate cancer biochemical recurrence and poorer overall survival." (PMID 32056047, 2020).
prostate carcinoma (continued). "In fact, IL-6 has been implicated as a prime contributory element responsible for the development of cachexia in prostate cancer patients." (PMID 32585812, 2020). "In Pten-deficient murine model for prostate cancer, inhibition of IL-6 suppressed high-fat diet-mediated prostatic inflammation and subsequent cancer progression." (PMID 32824865, 2020). "Radiotherapy in patients with prostate cancer causes inflammation leading to an increase in the circulating levels of IL-6, IL-8, TNF-α and TGF-β8." (PMID 33149212, 2020). "Our previous studies manifested that endothelial cells promoted the metastasis of prostate cancer by enhancing autophagy and increasing IL-6 secreion, which indicated that endothelial cells are associated with prostate cancer progression." (PMID 33425737, 2020). "The expression of CD44 in prostate cancer is significantly associated with tumor aggressiveness, and IL-6 signaling leads to a suitable microenvironment for the induction of CD44 expression." (PMID 31315262, 2019). "Expression of PSCA and IL-6 were significantly associated with poor survival of patients with prostate cancer." (PMID 31083587, 2019). "In conclusion, CD44 expression is significantly associated with tumor aggressiveness in prostate cancer and activation of IL-6 signaling leads to a suitable microenvironment for the induction of CD44 expression." (PMID 31315262, 2019). "Soy bread consumption for 56 days reduced MDSC-associated cytokines (IL6, GM-CSF, G-CSF, and CSF-1) and M-MDSCs in peripheral blood of prostate cancer patients with asymptomatic biochemical recurrence." (PMID 31408948, 2019). "In fact, it was shown that AR loss in prostate cancer cells favors stem-like phenotype and triggers IL-6 production, which in turn activates Stat3." (PMID 31366128, 2019). "Previous studies have shown that inflammatory cytokines, including CRP, IL-6, and IL-17, are positively associated with the risk of prostate cancer." (PMID 31088536, 2019). "Corroborating the observations in BC patients, IL-6 serum levels are higher compared to healthy controls also in lung, bladder, ovarian, head and neck, and prostate cancer, and in all cases the IL-6 serum level is associated with worse prognosis." (PMID 30658426, 2019). "The baseline OC-2-KB system did not return any results, while the retrained OC-2-KB extracted the assertion that <“interleukin 6”-“oc:associated with”-“prostate cancer risk” >." (PMID 30066655, 2018). "This is also consistent with prior observations where IL-6 undergoes transition from a growth inhibitor associated with neuroendocrine differentiation to a growth stimulator during prostate cancer cell progression." (PMID 30119678, 2018). "According to inclusion and exclusion criteria, the association of the IL-6 -572G/C polymorphism with prostate cancer was searched in databases and analyzed using comprehensive meta-analysis software." (PMID 30602952, 2018). "IL6 cytokine signalling axis has been implicated in prostate cancer progression and treatment resistance." (PMID 29540470, 2018). "Similar counterintuitive increase in metastatic burden following anti‐IL6 treatment was recently reported in Pten‐deficient prostate cancer model." (PMID 29540470, 2018). "Importance of molecular events such as SPRY2 loss or HER2 activation in tumoral IL6 production in clinical prostate cancers needs further investigation." (PMID 29540470, 2018). "Prostate cancer cells used in this study expressed IL-6 as a response to immune attack that seemed to be associated with the IGF-1Ec upregulation and PEc secretion, through the activation of JAK2/STA3 pathway." (PMID 30134795, 2018). "Although our study provides a better understanding of the IL-6 −572G/C polymorphism and susceptibility to prostate cancer, it has limitations." (PMID 30602952, 2018).
prostate carcinoma (continued). "These factors are particularly important in prostate cancer as both systemic cholesterol homeostasis and pro‐inflammatory cytokines such as IL6 have been implicated in CRPC." (PMID 29540470, 2018). "Several studies have shown an association between the IL-6 gene −572G/C polymorphism and the risk of prostate cancer, but the results are inconclusive." (PMID 30602952, 2018). "TLR4 expression and its attendant chronic inflammation (e.g., IL-6) are associated with faster progression and poorer treatment outcomes in prostate cancer." (PMID 29928275, 2018). "They found that preoperative serum levels of IL-6 higher than 1.2 pg/mL in men with prostate cancer were associated with an increased probability of biochemical recurrence (i.e., increased serum PSA levels)." (PMID 28292326, 2017). "Polymorphisms of IL-6 gene have been associated with prostate cancer risk; however, bona fida evidence of IL-6 as a sole factor in prostate cancer risk is lacking." (PMID 28077171, 2017). "Expression of IL-6 is associated with the development of prostate cancer through an immunomodulatory dialog with cancer cells." (PMID 28356100, 2017). "The strength of the correlation between IL-6 rs1800795 polymorphism and prostate cancer risk was evaluated using pooled odds ratios (ORs) with their 95% confidence intervals (95% CIs)." (PMID 28296724, 2017). "An increased serum interleukin-6 level has been linked to a lower serum total cholesterol level in patients with prostate cancer." (PMID 29156768, 2017). "The causative role of the pro-inflammatory cytokine IL-6 in prostate cancer progression has been well established at molecular level." (PMID 28077171, 2017). "Recently, PBMCs, the active lymphocyte and monocyte fraction of the blood, were shown to be associated with prostate cancer development, through the secretion of pro-inflammatory cytokines most notably IL-6." (PMID 28356100, 2017). "Elevated IL-6 serum levels have also been associated with metastasis-related morbidity in prostate cancer patients." (PMID 27577074, 2017). "STAT-3 signaling (closely associated with IL-6) was antagonized using siRNA in metastatic PC3 prostate cancer cells." (PMID 26828526, 2016). "There is accumulating evidence that elevated serum IL-6 levels are associated with advanced tumor stages in patients with prostate cancer." (PMID 27129164, 2016). "Increased levels of NF-κB and IL-6 are implicated in the development of prostate cancer cell chemoresistance." (PMID 27129164, 2016). "Consistent with this notion, IL-6 an inflammatory cytokine has been reported to cause human prostate cancer, and is associated with morbidity and mortality when there are increased levels." (PMID 28039439, 2016). "Several pieces of evidences have associated IL-6 with an aggressive prostate cancer phenotype and metastatic processes through the regulation of EMT and the homing of cancer cells to the bone." (PMID 27732936, 2016). "IL-6 stimulated growth of LNCaP cells and elevated IL-6 was also associated with poor prognosis in prostate cancer." (PMID 26683658, 2015). "Relevant to cancers, IL-6 activates STAT3 signaling pathways and high levels of IL-6 is associated with poor prognosis in a variety of cancers such as prostate cancer, bladder cancer, ovarian cancer, colorectal cancer and GC." (PMID 25928408, 2015). "Increased serum levels of IL-6 in prostate cancer patients were found to be associated with androgen-independence and metastatic disease, and overexpression of IL-6 was associated with protection of LNCaP cells from apoptosis during androgen depletion." (PMID 24296978, 2014). "In the present study, we determined the effect of atorvastatin and celecoxib administration alone or in combination on IL-6 levels in androgen-dependent prostate cancer LNCaP cells grown in androgen-deficient medium." (PMID 24296978, 2014).
prostate carcinoma (continued). "Our studies indicate that the effects of atorvastatin in combination with celecoxib on prostate cancer LNCaP cells are associated with inhibition of the IL-6 signaling pathway." (PMID 24296978, 2014). "Collectively, these results demonstrated that let-7 downregulation confers the reactive stromal phenotypes of prostate cancer-associated MSCs through its target gene IL-6." (PMID 23977098, 2013). "Taken together, our data demonstrated that MSCs co-evolve with prostate cancer cells in the tumor microenvironment, and the downregulation of let-7 by cancer-associated MSCs upregulates IL-6 expression." (PMID 23977098, 2013). "Previous studies showed that inflammatory cytokines IL-6 and IL-8 are associated with prostate cancer and elevated during metastasis." (PMID 24062781, 2013). "Earlier, MCL-1 was implicated in anti-apoptotic signaling by IL-6 in LNCaP and Du145 prostate cancer cells, whereas downregulation of MCL-1 lead to apoptosis in two days." (PMID 24040284, 2013). "Our data indicate that IL-6 expression was linked with irradiation and the biological changes following irradiation for prostate cancer." (PMID 23806095, 2013). "On the other hand, we found that carriers of the IL6-597 G-allele were at increased risk for high-grade prostate cancer." (PMID 22792137, 2012). "Elevated IL-6 and its soluble receptor have been linked to aggressive prostate cancer features including increased tumor volume, elevated overall Gleason score, distant metastases and decreased survival." (PMID 22641253, 2012). "IL-6 acts as an autocrine growth factor in prostate cancer and has been linked to progression of tumors." (PMID 22046235, 2011). "Decreased expression of ANXA1 has been associated with prostate cancer and was postulated to enhance tumor aggressiveness via the induction of IL-6." (PMID 20021671, 2009). "A poor prognosis has been consistently associated with high levels of serum IL-6 in patients with renal cell, ovarian, and prostate cancer." (PMID 12454774, 2002). "The DELC study suggested that high baseline serum IL-6 levels at the time of enzalutamide administration may lead to a poor prognosis and that IL-6 in the serum may cause the progression of prostate cancer independently of AR." (PMID 38305451, 2024). "Moreover, KRAS_SIGNALING_DN has been associated with gastric and glioblastoma cancers, and IL6_JAK_STAT3_SIGNALING is implicated in the progression of gliomas, bladder, and prostate cancers." (PMID 39691602, 2024). "The peripheral blood cytokines are closely associated with the occurrence and development of prostate cancer, especially the serum levels of IL-6 and IL-17A may be useful as potential predictors of PCa diagnosis." (PMID 38833027, 2024). "Some of the regulators affected by this treatment however could be implicated in anti-tumorigenic activities (i.e., IL-6), yet modulation identified in other regulators are potentially implicated in prostate cancer tumorigenesis, such as BHLHE40, and SRF." (PMID 38078010, 2023). "This MR study suggests that long-term IL-6 may increase the risk of prostate cancer and IL-1ra may reduce it." (PMID 36733309, 2023). "We used the replication to further support the causal effect of IL-1ra and IL-6 on prostate cancer." (PMID 36733309, 2023). "However, there is the possibility that these stimulating effects of MSCs promote the growth of tumor cells or their migration, as recently suggested by a study on the prostate-cancer-associated MSCs and their secretion of IL-6, the target of let-7 miRNAs." (PMID 37239986, 2023). "Similarly, a study with high-risk prostate cancer patients participating in physical exercise demonstrated improvements in fatigue along with a decrease in pro-inflammatory cytokines such as IL-1, IL-6, and TNF-α." (PMID 37507961, 2023).